LCN2 (lipocalin 2)
Diseases named in the same sentence as LCN2 in open-access papers (continued):
Sharing a sentence is not in itself a finding about the gene and the disease.
breast carcinoma (continued). "We conclude that NGAL/lipocalin-2 does not invariably affect the aggressiveness of breast cancers as assessed in mouse models, thus questioning the role of lipocalin-2 in cancer development." (PMID 22737251, 2012). "In a breast cancer mouse model, plasma samples from preclinical tumor-bearing mice compared with control mice show an upregulated protein expression of S100A8, S100A9, and LCN2." (PMID 22559235, 2012). "Elevated lipocalin 2 (LCN2) levels has also been reported in tissue- and urine samples from patients with invasive breast cancer and is proposed as a noninvasive biomarker for advanced breast cancer." (PMID 20078854, 2010). "Although lipocalin 2 have been demonstrated to correlate with breast cancer, the roles of lipocalin 2 in breast cancer formation and metastasis have not been clearly shown." (PMID 19077278, 2008). "And, the MMP-9/lipocalin 2 complexes were detected in 90% of urine samples obtained from breast cancer patients, but not in those from healthy controls." (PMID 19077278, 2008). "In addition, the LCN2/MMP9 complex is present in the urine of 86.36% of patients with breast cancer but is not detected in healthy donors." (PMID 40109857, 2025). "Notably, macrophage-derived LCN2 was found to donate iron to cancer cells, enhancing tumor growth, in a 3D tumor spheroid model established by stable LCN2R knockdown MCF-7 and MDA-MB-231 breast cancer cells." (PMID 39188682, 2024). "However, disruption of the LCN2 gene suppressed primary mammary tumor formation in mice, while not reducing lung metastases." (PMID 36926025, 2023). "Since MΦ-derived Lcn-2, but not FPN was associated with tumor onset and metastasis in an experimental mammary tumor model as well as with the recurrence status of breast cancer patients, we propose Lcn-2 as a promising candidate influencing the disturbed tumor iron homeostasis." (PMID 33808732, 2021). "These predicted interactions may explain the results observed when inhibitor ZINC00784494 and inhibitor ZINC00640089 were tested against non-expressing-LCN2 breast cancer cells (MCF7) and LCN2-overexpressing clones (MCF7-LCN2)." (PMID 34445288, 2021). "In the present study, we provide evidence that both FPN and Lcn-2 mRNA expression analyzed in whole tissue samples is not regulated in breast cancer, examined by TCGA data base analysis as well as in the experimental PyMT spontaneous murine breast cancer model." (PMID 33808732, 2021). "Notably, a significant correlation between LCN2 expression with other markers including ER− negative or progesterone receptor (PR)-negative status has been reported in breast cancer." (PMID 34072157, 2021). "However, disruption of the LCN2 gene in mice suppresses primary mammary tumor formation, whereas it does not decrease lung metastasis." (PMID 34202288, 2021). "Finally, it is interesting to note that while previous studies have identified LCN2 as a promising therapeutic target to abrogate progression and metastasis in breast cancer, other work has suggested that LCN2 is not necessary for metastasis." (PMID 31105883, 2019). "Furthermore, the LCN2 promoter non-methylated status (67.2%) is much higher than its methylated status (32.8%) in breast cancer patients." (PMID 27912767, 2016). "LCN2 expression has been associated with ER negative, PR negative and HER2 positive breast cancers." (PMID 22559235, 2012). "This could explain why the lack of lipocalin-2 production in our knock-out mice did not have any effect on mammary cancer development in the FVB/N mouse strain." (PMID 22737251, 2012). "However, the roles of lipocalin 2 in breast cancer formation and metastasis have not been clearly shown." (PMID 19077278, 2008). "However, in breast cancer leptomeningeal metastasis, macrophages do not produce LCN2 themselves." (PMID 39188682, 2024).
breast carcinoma (continued). "In supportive of our hypothesis, higher LCN2 expression was associated with worse DSS (HR 1.36, 95% CI 1.09–1.57, p = 0.003), PFI (HR = 1.31, (95% CI = 1.134–1.65, p = 0.001), but not for OS (p = 0.43) among breast cancer patients of the METABRIC cohort." (PMID 34072157, 2021).
Insulin resistance (135 papers, 2008 to 2026). Increased resistance towards insulin, that is, diminished effectiveness of insulin in reducing blood glucose levels. "Among them, Egr1, Lcn2 and Socs3 were more abundant in liver and closely associated with insulin resistance." (PMID 40523992, 2025). "Emerging adipokines such as resistin, chemerin, visfatin, omentin, and lipocalin-2 have been linked to regulating inflammation, insulin resistance, and neuroimmune interactions." (PMID 40725107, 2025). "Other preclinical and clinical studies of T2D have found an increase in circulating LCN2 associated with greater insulin resistance and hyperglycemia through promoting systemic inflammation and activation of the immune system." (PMID 39808380, 2025). "Although controversial, increased circulating LCN2 is typically associated with insulin resistance and increased inflammation." (PMID 37237488, 2023). "LCN2 has also been proved to be an inflammatory marker closely associated with insulin resistance and hyperglycemia." (PMID 34212049, 2021). "Additional studies support diabetic and obesogenic effects of Lcn2 where, Lcn2 deficiency attenuated insulin resistance and the percentage body weight gain and blood glucose levels were lower compared to WT mice." (PMID 32883997, 2020). "LCN-2 deficient mice show insulin-sensitive metabolic properties by inhibition of arachidonate 12-lipoxygenase, which is related to insulin resistance and inflammation." (PMID 32982804, 2020). "Lipocalin-2 (LCN2) is mainly secreted by activated neutrophils and associated with neurodegeneration, inflammatory responses, insulin resistance, and atherosclerotic disease." (PMID 31467617, 2019). "On the other hand, Guo and co-workers showed opposite results, that is Lcn2 deficiency potentiated diet-induced insulin resistance in mice." (PMID 28529490, 2017). "The gene expression of lipocalin-2, which is an adipokine implicated in insulin resistance and a secretory protein with lipid-binding prosperities, was increased by about 10 times." (PMID 28439422, 2017). "It has been reported that LCN2 is an adipokine that seems to be an independent risk factor for hyperglycemia and insulin resistance in humans." (PMID 21526992, 2011). "The overexpression of Dusp1, Insig2, and Lcn2 has been linked to the development of insulin resistance." (PMID 21187916, 2010). "This study demonstrates that hsCRP and Lipocalin-2 are associated with early glucose metabolism abnormalities and may serve as markers for insulin resistance and inflammation in prediabetes and T2DM." (PMID 40951890, 2025). "Conversely, LCN2 deficiency improves insulin resistance and diabetic encephalopathy." (PMID 38201988, 2024). "In our article, we focused only on selected ones—nesfatin-1, preptin, myonectin, omentin-1, gremlin-1, galectin-3, neuregulin-4, xenopsin-related peptide, xenin, neudesin, and lipocalin-2—and investigated their associations with insulin resistance in patients with PCOS." (PMID 35206286, 2022). "It has been confirmed, in animal studies that LCN2 deficiency may protect from the development of insulin resistance through regulation of lipoxygenase and cachexin levels in adipose tissue." (PMID 35206286, 2022). "Elevated levels of lipocalin-2 may be associated with obesity, hypertriglyceridemia, hyperglycemia, markers of insulin resistance, and declining pancreatic β-cell function." (PMID 34769010, 2021). "Finally, LCN2‐deficient mice display increased insulin resistance under hyperglycemia and heightened blood glucose levels compared to control mice." (PMID 33945675, 2021). "These markers were galectin-3, MMP-9, lipocalin-2 (NGAL, a novel adipokine associated with insulin resistance), PIIINP (the amino-terminal peptide of type III procollagen, released into the blood during both synthesis and degradation of collagen type III), hsCRP, and NLR." (PMID 28785588, 2017).
Insulin resistance (continued). "This might indicate their susceptibility to develop complications associated with LCN2 such as metabolic syndrome, insulin resistance, ischemic heart diseases and diabetic kidney diseases." (PMID 28709459, 2017). "We found that fasting serum insulin and HOMA-IR were clearly associated with lipocalin-2 even in stepwise regression analysis, suggesting that this protein might be an indicator for β cell function and insulin resistance in humans." (PMID 22292925, 2012). "Lipocalin 2 (Lcn2) is an adipokine that is abundantly expressed in adipose tissue, largely in response to metabolic stress; TE deficiency is expressed in metabolic dysfunction as increased oxidative stress, the development of dyslipidaemia and insulin resistance." (PMID 35722455, 2022). "LCN2 as an inflammatory marker can activate the STAT3 signaling pathway by its receptor 24p3R to exacerbate insulin resistance, nonalcoholic steatohepatitis and obesity." (PMID 40523992, 2025). "The results presented here are consistent with previous reports indicating that LCN2 levels are elevated in T2D and this increase contributes to the development of the disease by promoting insulin resistance and hyperglycemia." (PMID 39808380, 2025). "RBP4 and LCN2 correlate with insulin resistance and cardiovascular disease burden, and elevated circulating levels predict adverse outcomes and event severity in CAD populations." (PMID 41303567, 2025). "Pro-inflammatory adipokines such as RBP4 and LCN2 contribute to insulin resistance, oxidative stress and endothelial dysfunction." (PMID 41303567, 2025). "It is pertinent to highlight that before LCN2 blockade with the antibody, at 18 weeks of age, all mice subjected to T2D induction exhibited hyperglycemia, insulin resistance, and glucose intolerance." (PMID 39808380, 2025). "There is a positive correlation between NLRP3 and LCN2 expression, underscoring the pathophysiological relevance of this axis in metabolic dysfunction and insulin resistance." (PMID 41303567, 2025). "In the group combining RES and Pilates, there was a significant increase in sestrin 2 (SESN2) and GPX and a decrease in lipocalin-2 (LCN2), the homeostatic model assessment of insulin resistance (HOMA-IR), and malondialdehyde (MDA)." (PMID 40077707, 2025). "Conversely, LCN2 treatment suppressed appetite, improved glucose tolerance and insulin resistance, and decreased body weight in lean and obese mice." (PMID 38035773, 2024). "In mice with osteoblast specific knockout Lcn2 gene (Lcn2 osb−/−), serum levels of LCN2 were decreased by 67%, and impaired glucose tolerance, insulin resistance, and increased body weight, fat mass, and food intake was observed after glucose loading." (PMID 37326909, 2024). "In short, with the deterioration of glucose homeostasis and the occurrence of insulin resistance, bone begins to secrete LCN2 into circulation as a compensatory response to suppress food intake and increase energy metabolism." (PMID 38035773, 2024). "If glucose dysregulation continues to increase, LCN2 acts as an adaptive factor that improves β‐cell proliferation and function to counteract insulin resistance and curbs hyperglycemia." (PMID 38035773, 2024). "On the contrary, several studies showed that Lcn2 knock out mice gained more weight, developed dyslipidemia and insulin resistance with high-fat diet compared to their wild-type littermates." (PMID 37326909, 2024). "The involvement of Lcn2 in apoptosis extends to insulin resistance, cancer, and nervous system diseases." (PMID 37864452, 2024). "Molecules such as TNF-α, IL-1β, and NF-κB and their signaling pathways positively regulate LCN2 expression and are involved in the induction of insulin resistance." (PMID 38673873, 2024). "The critical role of LCN2 in metabolic disorders has been demonstrated by studies using LCN2-knockout mice that gained more weight and developed dyslipidemia and insulin resistance." (PMID 38672227, 2024).
Insulin resistance (continued). "In sum, it is obvious that additional work is required to understand LCN2’s roles in the pathogenesis/prevention of insulin resistance." (PMID 37638032, 2023). "It has also been proven that the level of LCN2 is closely related to insulin resistance and hyperglycaemia." (PMID 38203346, 2023). "Nevertheless, another study has shown that LCN2-deficient mice exhibit potentiated DIO and insulin resistance, impaired adaptive thermogenesis, and enhanced AT inflammation." (PMID 35406450, 2022). "In accordance with the fact that circulating LCN2 level is increased in insulin resistance and type 2 diabetes, its serum level was also elevated in HFD/STZ-induced diabetic mice." (PMID 35884685, 2022). "Recently, it was shown that LCN2 is positively correlated with insulin resistance and inflammation in humans." (PMID 36329549, 2022). "Soon afterward, interest was attracted to the relationship between LCN2 and metabolic disorders, as LCN2 has a critical effect on lipid metabolism and insulin resistance." (PMID 35034646, 2022). "Regarding the role of LCN-2 in metabolic syndrome, increased lipid accumulation and insulin resistance were attenuated in LCN-2 knockout mice." (PMID 35056647, 2022). "Our study focused on the effect of LCN2 on apoptosis which is involved in the pathogenesis of insulin resistance, cancer, and nervous system diseases." (PMID 34903175, 2021). "The study of Milner and colleagues showed that LCN2 levels correlated with the degree of liver inflammation and the stage of hepatic fibrosis as well as insulin resistance." (PMID 33799862, 2021). "Lcn2 is induced by factors that drive insulin resistance and inflammatory stimuli, with transactivation by the pro-inflammatory transcription factor NF-κβ." (PMID 33528828, 2021). "It was concluded that adipose excreted LCN2 contributes to dysregulation of metabolism in females, and liver LCN2 seems to act on metabolic traits of males, specifically on insulin resistance." (PMID 33799862, 2021). "In another study, mice with systemic LCN2 overexpression, exhibited enhanced fat mass and adipocyte size, accompanied by increased food intake, glucose intolerance, and insulin resistance." (PMID 32544571, 2020). "New theories about the character of adipose tissue and the cytokines released by them have suggested correlations between adipokines such as LCN-2 and their role in preventing systemic insulin resistance and, thus, MetS." (PMID 32983730, 2020). "Nevertheless, LCN2 treatment promoted insulin resistance in H4IIe hepatocytes (250 ng/mL) and human adipose tissue (100 ng/mL), and LCN2 knockdown in 3T3-L1 adipocytes increased insulin sensitivity." (PMID 32544571, 2020). "We previously demonstrated that the same HFHC used in the current study increases Lcn2 mRNA expression in the hippocampus in the presence of diet-induced insulin resistance." (PMID 31892368, 2019). "Serum LCN2 concentrations were found to be increased in patients with metabolic syndrome, with a significant correlation between LCN2 and measures of insulin resistance." (PMID 30805373, 2019). "A role of LCN2 in insulin resistance and metabolic derangement induced by HFD is highly and surprisingly controversial." (PMID 29138470, 2017). "The Lipocalin Lcn2 reduces lysosomal degradative activity, resulting in insulin resistance in cardiomyoblasts." (PMID 28182653, 2017). "Together with human studies, the general consensus is that Lcn2 is overexpressed during insulin resistance." (PMID 27538526, 2016). "A study that investigated the development of NAFLD in Chinese subjects revealed a close correlation of serum LCN2 with the progression of the disease and the occurrence of insulin resistance." (PMID 27729871, 2016). "Lipocalin-2 (also known as 24p3, neutrophil gelatinase-associated lipocalin and siderocalin) and retinol binding protein 4 (RPB4) are novel adipokines that contribute to insulin resistance and type 2 diabetes in obese rodents." (PMID 23799122, 2013).
Insulin resistance (continued). "The adipokine LCN2 is central to cell defense, leads to sustained chronic inflammation and protects aging mice from insulin resistance." (PMID 21573245, 2011). "The expression of lipocalin-2, an adipokine promoting insulin resistance, was far higher in SVCs from iWAT than eWAT." (PMID 21687689, 2011). "Lipocalin-2 is a novel adipokine that appears to play a role in the development of insulin resistance." (PMID 21143924, 2010). "Circulating lipocalin-2 concentrations positively correlate with adipocyte mass, hypertriglyceridemia, hyperglycemia and insulin resistance." (PMID 18721461, 2008). "Furthermore, the increase in LCN2 engages in the development of hyperglycemia and insulin resistance, and blocking this protein can be an effective treatment for T2D." (PMID 39808380, 2025). "Some reports have shown that LCN2 inhibition promotes the development of diet-induced insulin resistance, while LCN2 administration enhances pancreatic β-cell proliferation increases insulin production and reduces insulin resistance and blood glucose levels in mice with type 2 diabetes." (PMID 39808380, 2025). "Thus, we suggest that levels of circulating LCN2 as an adipokine increase in ob/ob mice with insulin resistance." (PMID 39832399, 2025). "Accordingly, LCN2 regulates the gut microbiota composition and intestinal permeability, i.e., factors that may lead to systemic inflammation, insulin resistance, metabolic syndrome, and related characteristics." (PMID 39744637, 2024). "The authors of this study also observed the positive correlations between LCN2 and features of insulin resistance: fasting plasma glucose (FGP), HOMA-IR, fasting plasma insulin (FPI), high-sensitivity C-reactive protein (hs-CRP), total cholesterol and triglyceride." (PMID 38203346, 2023). "Among them, Lcn2 and Angptl2 have been reported to promote inflammation and insulin resistance." (PMID 35655797, 2022). "Moreover, the reduction of insulin resistance through the in vitro treatment or in vivo supplementation of thiazolidinediones reduces adipocyte and AT LCN2 expression." (PMID 35406450, 2022). "As expected, we found that LCN2 deletion reduced insulin resistance and hepatic steatosis." (PMID 35884685, 2022). "It is important to clarify the effect of LCN2 on apoptosis that might contribute to the pathogenesis of insulin resistance, cancer, and various nervous system diseases." (PMID 34903175, 2021). "It is suggested that LCN2 may be a significant key to the pathogenesis of inflammation, leading to insulin resistance, followed by an increase in fasting plasma glucose and fasting plasma insulin." (PMID 34212049, 2021). "Several publications are in contradiction regarding the role of LCN2 in insulin resistance in mice." (PMID 34638803, 2021). "However, our previous research demonstrated that LCN2 overexpression in ob/ob mice exacerbates insulin resistance, inflammation, and oxidative stress in adipose tissue, heart, and brain." (PMID 34064680, 2021). "Moreover, LCN2 blood levels are positively correlated with insulin resistance in females, as demonstrated in some clinical studies." (PMID 33945675, 2021). "Lcn2 knockout mice also revealed the important metabolic effects of NGAL/LCN2, with higher body and adipose tissue weight in Lcn2 KO than wild type mice, as well as insulin resistance, but a benefit of LCN2 was also been reported in beiging of adipocytes and increased thermogenesis." (PMID 33510370, 2021). "In addition, LCN2 levels were positively correlated with adiposity, hypertriglyceridemia, hyperglycemia, and insulin resistance index but negatively correlated with HDL cholesterol." (PMID 31736870, 2019). "LCN2, a small secreted transport protein, was initially recognized for its role in innate immunity and was then identified as an adipokine capable of inducing insulin resistance." (PMID 31736870, 2019).